BRAF (B-Raf proto-oncogene, serine/threonine kinase)
Diseases named in the same sentence as BRAF in open-access papers (continued):
Sharing a sentence is not in itself a finding about the gene and the disease.
tumor (continued). "The EGFR pathway signals through Kras/Braf and although EGFR/c-Erb-B2 amplifications are rare in CRC, gain-of-function mutations in KRAS/BRAF are extremely common and are seen in up to 60% of tumours." (PMID 21698197, 2011). "Standard mutational testing for BRAF in tumor tissue typically utilizes techniques such as bidirectional direct fluorescent sequencing and allele-specific polymerase chain reaction which are commercially available and offer high specificity." (PMID 22175026, 2011). "In accordance with previous reports, BRAF mutation occurred more frequently in right-sided tumour locations." (PMID 21285991, 2011). "BRAF mutations were mutually exclusive with KRAS mutations, and four BRAF mutations were found in tumours with MSI." (PMID 21901162, 2011). "A total of 86 (63.7%) patients with wild/wild tumours and five (33.3%) patients with BRAF mutation-positive tumours received anti-EGFR therapy, whereas few patients with KRAS12 or KRAS13 mutations received anti-EGFR therapy (1.9% and 3.8%, respectively)." (PMID 21285991, 2011). "KRAS and BRAF mutations were mutually exclusive, whereas, three tumours carried both KRAS and PIK3CA mutations." (PMID 21283802, 2011). "The presented data demonstrate that the patients with the BRAF V600E mutation have worse prognosis than the patients with wt-BRAF tumour and progress early during treatment." (PMID 22933967, 2011). "BRAF mutations were correlated with proximal tumour location: 7 of 36 proximal (19.4%) and 2 of 58 distal (3.5%) tumours were mutated (P = 0.0323)." (PMID 21901162, 2011). "It has been demonstrated that BRAF mutation in thyroid microcarcinomas correlates with either high rate of extrathyroidal tumor extension or lymph node metastasis." (PMID 22654559, 2011). "Specifically, the relative risk of death for patients with BRAF mutation was 4.23 (95% CI 1.76–10.2) compared with patients with wt BRAF tumours (P=0.001)." (PMID 21285991, 2011). "CIMP and BRAF mutation are hallmarks of serrated tumours and BRAF V600E has been proposed as an important biological marker for HPS specific cancers." (PMID 21347319, 2011). "In the phase I study, tumour biopsies from nine patients were analysed for mutation status of BRAF and RAS; normal skin samples were available from seven of the nine patients." (PMID 21750549, 2011). "In the present study, we also found that CIMP-high CRCs were more frequently associated with proximal tumor location, poorly differentiated histology, mucinous histology, BRAF mutation, and MSI-high status compared to their CIMP-low/negative counterparts." (PMID 21827707, 2011). "Of the nine tumour samples, 5 had activating mutations in exon 15 of BRAF; four were V600E BRAF mutations and one was a V600K BRAF mutation." (PMID 21750549, 2011). "Six of 9 BRAF mutated tumours showed MSI, and all of those had the MLH1 promoter methylated and were proximally located." (PMID 21901162, 2011). "BRAF analysis on free DNA in the serum and plasma has been reported as has the detection of BRAF mutations from isolated, circulating tumor cells (CTCs)." (PMID 22175026, 2011). "It is possible that acquisition of a mutation, such as KRAS or BRAF, represents the moment of transition from a benign tumour to an LMP." (PMID 22163003, 2011). "Mutually exclusive somatic mutations in either KRAS or BRAF are often reported in LMP tumours and LGOSCs (30–50%), but rarely in HGOSCs (<12%)." (PMID 22163003, 2011). "When only KRAS WT cases were analyzed patients whose tumours carried the BRAF mutation had even more significantly lower TTP and OS (TTP: 2.1 vs. 6.4 months, p<0.0001; OS: 4.3 vs. 16.3 months, p <0.0001) compared with the results in the whole population." (PMID 21283802, 2011). "In conclusion, we studied the prevalence of PIK3CA, RAS (KRAS, NRAS), and BRAF mutations in diverse tumor samples and identified a high frequency of coexisting PIK3CA and BRAF or RAS mutations." (PMID 21829508, 2011).
tumor (continued). "To add to our knowledge of this rare entity, we have determined the mutational status of the BRAF gene in tumour tissue of the patient." (PMID 21827678, 2011). "If the BRAF mutation is also found to cause a down regulation of tumor antigens in HCL, this would provide a compelling explanation for why two seemingly disparate diseases are among the rare responders to the actions of IFN-α." (PMID 24213115, 2011). "BRAF-wild-type clones present in primary tumours and metastases are likely to contain mutations or copy number alterations affecting genes other than BRAF, such as NRAS, KIT, cyclin D1, PTEN and CDKN2A." (PMID 21224857, 2011). "Conventional direct sequencing of PCR products of BRAF exon 15 revealed that three tumours harboured the V600E mutation, one tumour had the V600K mutation, and the remaining six tumours were wild type." (PMID 21224857, 2011). "Recently, however, it has been shown that the rate of BRAF mutations that have been associated with a more aggressive tumor type in papillary thyroid carcinomas has increased over time." (PMID 22496986, 2011). "Patients with BRAF-mutated primary tumours had a significantly decreased PFS (2.7 vs 9.8 months; P<0.001) and median OS (14 vs 30 months; P<0.001) than patients with wild-type (wt) tumours." (PMID 20485284, 2010). "BRAF mutations have also been shown to be associated with extrathyroidal invasion, lymph node metastasis, and advanced tumor stage hence conferring a worse clinical prognosis compared to BRAF wild-type." (PMID 20862373, 2010). "This is consistent with this distinct subset of tumours arising by a mechanism of microsatellite instability, which is strongly associated with BRAF mutation." (PMID 20233436, 2010). "BRAF mutations are associated with extrathyroidal tissue invasion, lymph node metastases and advanced tumor stage." (PMID 21048836, 2010). "The BRAF V600E mutation was detected in 12 (8%) patients and 22 (15%) tumours were characterised as MSI-H." (PMID 20485284, 2010). "In cellular studies, the compound inhibits ERK1/2 phosphorylation at subnanomolar concentrations, and exerts antiproliferative effects in multiple tumor cell lines harboring KRAS or BRAF mutations." (PMID 20149254, 2010). "The BRAF mutation was detected in 58 (17.3%) tumours: 19 (32.8%) of these were MSS and 39 (67.2%) were MSI-H." (PMID 20051945, 2010). "Univariate analysis revealed significant associations of PFS with undifferentiated tumour histology (P=0.001), BRAF mutations (P<0.001) and inability of patients to undergo metastasectomy (P<0.001)." (PMID 20485284, 2010). "If BRAF V600E mutations are present in MSI-H tumours, the possibility of LS can be nearly excluded, but only approximately 40–50% of MSI-H sporadic CRC tumours are reported to have BRAF mutations." (PMID 20051945, 2010). "PLX4032 showed both tumor shrinkage and delay in tumor progression in patients with the BRAF mutation and reports of improvement in clinical symptom." (PMID 24281185, 2010). "Similar to previous reports on CIMP+, the CIMP-H tumors in this study were significantly associated with older age, proximal tumor location and BRAF mutation relative to CIMP-M and CIMP-L tumors." (PMID 20492682, 2010). "The frequency of mutations for KRAS, PIK3CA, and BRAF were tested for correlation to the degree of differentiation and to the prevalence of mucin in the tumor." (PMID 20233444, 2010). "In cellular assays, the compound inhibits basal and growth factor-stimulated phosphorylation of ERK1/2 with IC50 concentrations < 40 nM, and exerts antiproliferative effects on tumor cell lines harboring BRAF or RAS mutations." (PMID 20149254, 2010). "The frequency of tumor mutations in either KRAS or BRAF increased with patient age, both when comparing age groups and with age as a continuous variable." (PMID 21103049, 2010). "Primary tumours from 144 patients treated for mCRC were assessed for BRAF (V600E) mutation, MSI status and cyclin D1." (PMID 20485284, 2010).
tumor (continued). "The median OS was 14 and 30 months for patients with BRAF-mutated and wt tumours respectively (P<0.001)." (PMID 20485284, 2010). "Laboratory Corporation of America (LabCorp) (Burlington, NC) BRAF Gene Mutation Detection Test (480340): This assay requires either an FFPE tissue block with ≥ 50% tumor or 4 unstained 5-μm slides and a single hematoxylin and eosin (H&E)-stained 5-μm slide." (PMID 20972475, 2010). "The detection of BRAF mutations was also correlated with cyclin D1 expression as cyclin D1 overexpression was detected in 58 and 14% of BRAF mutated and wt tumours respectively (P=0.001)." (PMID 20485284, 2010). "In this study, the incidence of BRAF mutations was significantly higher in patients with MSI-H (45%) than with MSS tumours (1.6% P=<0.001), in agreement with the published evidence." (PMID 20485284, 2010). "Univariate analysis showed significant associations of OS with age >65 years (P=0.03), undifferentiated (grade 3) primary tumours (P=0.02), colonic vs rectal location (P=0.02), solitary metastasis (P=0.008) and BRAF mutations (P<0.0001)." (PMID 19603024, 2009). "A principal finding was that BRAF mutation the primary tumour marks patients who carry an especially poor prognosis, regardless of specific treatment regimen." (PMID 19603024, 2009). "The concordance rate of cfDNA BRAF mutations with tumour BRAF mutations was 56%, which is consistent with that of other reports." (PMID 19861964, 2009). "In total, of the 96 cases with matched tumour and cfDNA data, the concordance in BRAF mutation detection was 76% (95% confidence interval 66–84%)." (PMID 19861964, 2009). "A recently published retrospective analysis of tumor samples from CAIRO2 demonstrated that BRAF mutations were associated with poor clinical outcome." (PMID 20016807, 2009). "In the present analysis, 13, 7 and 1 patient among 87 patients with KRAS codon 12 and 13 wild-type disease had tumour bearing BRAF V600E, KRAS codon 61 and KRAS codon 146 mutation, respectively." (PMID 19603018, 2009). "BRAF mutation status was assessed in serum-derived cfDNA from 126 patients enrolled into the study and from 94 matched tumour samples." (PMID 19861964, 2009). "If a BRAF mutation was present in tumour DNA, the pick up rate in cfDNA was 56% (95% confidence interval 40–70%)." (PMID 19861964, 2009). "In keeping with these data, only oncogenic BRAF mutations have been implicated in tumours of epithelial and neuroectodermal origin." (PMID 19603027, 2009). "Second, the frequency of BRAF mutation is especially high, up to 50%, in tumours with microsatellite instability (MSIhi), which otherwise carry a favourable prognosis." (PMID 19603024, 2009). "The classical BRAF point mutation occurring at codon 600, leading to the amino-acid change V600E, was observed in two primary tumours (2 out of 36=6%) and in the 2 (6%) related metastatic lesions." (PMID 19293803, 2009). "In the other four patients showing discordant molecular profiles between primary tumour and metastasis and for whom clinical data were available, the additional presence of either K-Ras or BRAF mutations at both sites predicted resistance to therapy." (PMID 19293803, 2009). "It should be noted that none of the 9 patients with a BRAF-mutant tumour responded to cetuximab, whereas objective responses occurred in 14 of 83 (17%) patients whose tumours carried WT BRAF alleles." (PMID 19603024, 2009). "Somatic mutations in the BRAF oncogene have been documented at a high frequency in cutaneous melanomas, occurring in up to 60% of cell lines and tumour samples." (PMID 19861964, 2009).
tumor (continued). "In conclusion, the T1799A BRAF mutation is present in a proportion of posterior uveal melanomas but within these tumours the distribution of the mutation is heterogeneous." (PMID 18985043, 2008). "If this is the case, tumours arising as a result of a mutation in either KRAS or BRAF should harbour similar downstream dependencies." (PMID 19018267, 2008). "MiRNA profiles were found to distinguish tumours containing the BRAF mutation from the other tumour types, and to differentiate between the more aggressive insular & anaplastic tumours, and the classic variant." (PMID 19055826, 2008). "Univariate analysis (Mann–Whitney U-test) showed that ECGF1 and GGH expressions were strongly associated with the CIMP+ features of proximal tumour site, TILs and BRAF mutation." (PMID 18414409, 2008). "CIMP+ tumours occur more frequently in the proximal colon of older patients and are associated with the microsatellite instability (MSI+) phenotype, tumour-infiltrating lymphocytes (TILs) and mutations in the BRAF oncogene." (PMID 18414409, 2008). "Except for sex, all of the other variables showed substantial changes in odds ratio (OR) for the association with CIMP-high after adjusting for MSI, BRAF and/or tumor location (or other variables)." (PMID 19002263, 2008). "Four BRAF mutations (1%) were found in the tumour set (G465V, N581S, L596R, and T599I) and one of these (N581S) occurred concurrently with LKB1 mutation (P=0.373)." (PMID 18594528, 2008). "In contrast to KRAS and PIK3CA mutations, BRAF mutations are associated with tumours harbouring CpG Island methylation phenotype (CIMP), MLH1 methylation and microsatellite instability (MSI)." (PMID 18782444, 2008). "In conclusion, we have shown that the BRAF mutation is present in a proportion of posterior uveal melanomas and that within these tumours the distribution of this mutation is heterogeneous." (PMID 18985043, 2008). "This technique was used to screen posterior uveal melanoma samples for the presence of the BRAF mutation and secondly to examine separate areas within individual tumours to confirm genetic heterogeneity." (PMID 18985043, 2008). "Initial reports of a low BRAF mutation frequencies in post-Chernobyl tumours and of a large impact of BRAF on gene expression raised the possibility of a radiation damage signature based on the mutational status of the tumours." (PMID 17712314, 2007). "In particular, these tumours are characterised by a high frequency of carrying BRAF mutation and a high frequency of CpG island methylation (CpG island methylator phenotype-high), and are considered precursor lesions of CRC with microsatellite instability." (PMID 17923875, 2007). "This suggests that K-ras/BRAF mutations are less important to neoplasia in the distal colon, although neoplasm occurs in greater numbers in the distal colon than in the other locations." (PMID 17923875, 2007). "Results of the limit of detection experiments confirmed that the 1 base pair change in the BRAF mutation was detectable down to the level of 25% tumor when a homozygous mutant cell line was used as a control." (PMID 16606457, 2006). "Results of the limit of detection experiments confirmed that the one base pair change in the BRAF mutation was detectable by LCPCR down to the level of 25% tumor when a homozygous mutant cell line was used as a control." (PMID 16606457, 2006). "In the present study, results of the limit of detection experiments confirmed that the 1 base pair change in the BRAF mutation was detectable down to the level of 25% tumor when a homozygous mutant cell line was used as a control." (PMID 16606457, 2006). "Strong associations were observed between BRAF mutation and tumor origin in the proximal side of the large bowel, poor histological grade, mucinous appearance and the presence of infiltrating lymphocytes." (PMID 16403224, 2006).
tumor (continued). "The overall frequency of BRAF mutation was 8.4% (23/275), comparing favourably with frequencies of 9–11% reported for other large studies of this tumor type." (PMID 16403224, 2006). "Although screening of BRAF mutation in human tumours has widely been performed, to date the data on BRAF mutation in NHL tissues is lacking." (PMID 14612909, 2003). "Regulatory approvals of therapies targeting tumors harboring genomic alterations such as NTRK and RET fusions, BRAF V600E mutation, and those with deficient mismatch repair (dMMR) and a high tumor mutational burden (TMB-H) have demonstrated clinical activity across multiple cancer types." (PMID 42192928, 2026). "Moreover, in PTC, DUSP4 overexpression correlates with BRAF p.V600E mutation, highlighting a potential biomarker for tumor aggressiveness associated with cancer progression and metastasis formation." (PMID 41489907, 2026). "SLC1A5 is expressed exclusively by BRAF p.V600E mutated tumor cells in the thyroid." (PMID 41489907, 2026). "Additionally, one article proposed that the PTC microenvironment is composed of a mixture of tumor cells, with only a small portion carrying BRAF mutations." (PMID 40269951, 2025). "In addition, the patient’s age was highly significantly positively correlated with BRAF V600E mutation and tumor location, significantly positively correlated with tumor multifocality, and significantly negatively with the TI-RADS stage." (PMID 40632708, 2025). "Adjuvant anti-PD-1 therapy [I, A] or dabrafenib–trametinib for BRAF V600E-mutated tumours [I, A]." (PMID 39550033, 2025). "Other mutations, such as BRAF, were most often detected in all sampled regions of the tumour." (PMID 40302146, 2025). "While several studies have reported a higher prevalence of mutations, particularly BRAF V600E in older patients and their association with more aggressive tumor behavior, the relationship between age and mutation status has not been consistently demonstrated across different cohorts." (PMID 40748901, 2025). "However, its high expression in tumor samples was slightly lower than in metastatic samples, indicating that BRAF’s overexpression is associated with tumorigenesis, tumor aggressiveness, and progression to advanced stages." (PMID 41009348, 2025). "High ARSI expression was associated with tumor tissue and BRAF mutation." (PMID 39744439, 2025). "The tumor stage plays a primary role in prognosis, particularly in cases involving BRAF mutations." (PMID 40949797, 2025). ": Close monitoring of tumor response during treatment using multiple blood tests for circulating BRAF V600E mutation levels could provide real-time data on the tumor’s response to therapy." (PMID 40696244, 2025). "Additionally, some studies incorporated BRAF V600E, a variant associated with aggressive tumor behavior and poor prognosis." (PMID 40141130, 2025). "Additionally, reports have documented that patients with PM harboring a BRAF V600E mutation experienced significant tumor shrinkage and symptom relief following treatment with vemurafenib." (PMID 40904706, 2025). "The proportion of successfully tested tumours that were BRAF mutated was 34% (n = 4424/13 012)." (PMID 40902091, 2025). "In clinical practice, we recommend to perform panel or exome sequencing of tumor biopsies at initial diagnosis to determine potentially actionable gene mutations and fusions (including BRAF, FGFR, IDH1, IDH2, BRCA1, BRCA2, and NTRK) for further lines of therapy." (PMID 39809756, 2025). "For example, miR-31 and miR-135b have both been implicated in the serrated neoplasia pathway—particularly in lesions with high microsatellite instability—high and BRAF mutations—whereas miR-143 and miR-145 are commonly associated with AD–carcinoma sequences and KRAS or APC mutations." (PMID 40693022, 2025). "Also, there was no obvious contribution of clinical characteristics, such as tumor stage, BRAF mutation status, onset of immune-related adverse events, or therapy response to the clustering." (PMID 40795845, 2025).